PAX5 (paired box 5)
Diseases named in the same sentence as PAX5 in open-access papers (continued):
Sharing a sentence is not in itself a finding about the gene and the disease.
tumor (continued). "Interestingly, it was shown that re-expression of PAX5 in lung cells inhibited β-catenin signalling pathway, which plays important role not only in proliferation, differentiation, and migration but also in regulating immune cell infiltration of the tumour microenvironment." (PMID 31877723, 2019). "For this purpose, our first aim was to cultivate the tumor cells in 2D and 3D tissue culture systems and to determine whether the primary tumor tissue and cultured cells in 2D and 3D tissue culture systems had the same methylation signature for PAX5, TMPRSS2, and SBDS." (PMID 30792990, 2019). "For this reason, the primary objectives were to grow tumor cells in 2D and 3D tissue culture systems and to determine whether the cells grown in the culture systems and primary tumor cells had the same features of methylation in the genes PAX5, TMPRSS2, and SBDS." (PMID 30792990, 2019). "The tumor cells were diffusely positive for CD20, PAX-5, Bcl-2 and follicular dendritic cells were positive for CD21, CD23." (PMID 28353588, 2017). "The transformed tumor cells expressed CD30 positivity along with OCT-2 and PAX5 in the RS-like cells." (PMID 26380128, 2015). "Cells within the encapsulated mediastinal tumor stained strongly positive (+++) for CD45 and CD79a, PAX5, and CD20, and positive (+) for BCL-2 and MUM1." (PMID 26715530, 2015). "All PAX8-positive tumours were verified as positive using another PAX8 antibody raised against a region of the C-terminus, which exhibits a lower homology with PAX5." (PMID 24602166, 2014). "The long CpG islands of the PAX5 and RUNX2 genes neighboring a small number of retroelements at a long distance, > 6 kb, showed insignificant methylation alterations in the tumor tissues." (PMID 16827945, 2006). "Similarly, in immunohistochemistry, tumor cells express B‐cell markers (CD20, CD79α, PAX5), and most often exhibits a non‐germinal center phenotype (CD10−, MUM1+) along with high proliferation index (Ki‐67 > 80%)." (PMID 41567526, 2026). "We observed a negative correlation between FAP expression and the B-cell transcription factor PAX5 in DLBCL, which further supports the notion that FAP may be regulated by factors related to B-cell differentiation and tumor phenotype." (PMID 41373408, 2025). "Accordingly, we found a significant negative correlation (p = 0.022, ρ = −0.38) between the expression levels of FAP and PAX5 in the DLBCL and FL tumor tissues, and FAP expression further showed a negative correlation with bone marrow involvement at the time of diagnosis (p = 0.028, ρ = −0.38)." (PMID 41373408, 2025). "In this case, subsequent analysis revealed negative PAX5 expression in the tumor cells, combined with weak CD20 expression, indicating the diagnosis of PBL." (PMID 40160869, 2025). "PAX5 transcripts are present at very low levels in normal tissue and are further reduced in tumours, whereas SALL4, ZNF770 and ZNF121 transcripts are upregulated in primary and metastatic tumours compared to normal colon." (PMID 40241172, 2025). "TFs like PAX5 and SPI1 might regulate the immune cell composition in the tumor, including myeloid cell recruitment." (PMID 41238550, 2025). "SCRIPro could accurately predicts well-known master regulators including SPI1, IRF1, FLI1, and STAT2 for mono/macrophages, GATA3, RUNX3, SMARCA4, JUND, and MYB for T-cells, PAX5, BCL2, and IRF4 for B and tumor B-cells." (PMID 39024032, 2024). "PAX5-ZCCHC7 structural variations are also observed in a subset of B-lymphoblastic leukemia (B-ALL), a neoplasm that demonstrates robust ZCCHC7 expression overall, and especially in treatment-refractory cases, with PAX5-ZCCHC7 positive cases showing the highest levels of ZCCHC7 mRNA expression." (PMID 38049665, 2023).
tumor (continued). "Among the responders, we observed the activation of the PAX5 network in the immune regions adjacent (spatial gene expression clusters in direct contact) to tumor clusters, while FOS and JUN modules are highly active in CAFs surrounding the tumor spots." (PMID 37723590, 2023). "The tumor cells in PBDLBCL are positive for CD45, CD20, CD79a, and PAX5 (B‐cell markers)." (PMID 40625579, 2023). "MUM1/IRF4 was also strongly positive in tumor cells, and considered together with PAX5 positivity, indicated the nongerminal center origin of this tumor." (PMID 36992464, 2023). "In immunohistochemistry (IHC), tumor cells were CD30 and PAX5 positive." (PMID 36614926, 2022). "Our digital image analysis approach and the use of PD-ligand/PAX-5 double staining technique allowed a reliable and consistent identification of tumor cells (PAX-5 positive) and leukocytes (PAX-5 negative)." (PMID 35326658, 2022). "In addition, PAX5 transcriptionally activates the expression of FOXP4-AS1 and FOXP4, exerting tumor-promotive effects." (PMID 36064939, 2022). "In contrast, CD40LG is moderately correlated with PAX5 (B cells, r = 0.45 and 0.46 in normal and tumor tissues, respectively), but not BATF3 (dendritic cells)." (PMID 34758832, 2021). "The tumor did not contain a significant population of B-cells or epithelial cells as determined by immunohistochemistry for Pax5 and MCK." (PMID 32498297, 2020). "IL-6+/-/Pax5+/- tumor DNA was derived from whole leukemic BM or lymph nodes, while tail DNA of the respective mouse was used as reference germline material." (PMID 33154497, 2020). "Moreover, immunohistochemical analysis revealed that tumor cells were positive for CD20, CD79a, PAX5, CD21, and CD23, and expression of CD3, CD5, and CD8 were observed in reactive T lymphocytes surrounding tumor cells." (PMID 33585230, 2020). "We observed no significant alterations in expression of pax5 (B cells) and pu1.1 (macrophages) in the tumor-bearing vs. control cohorts." (PMID 32582141, 2020). "We also investigated whether PAX5, SBDS, and TMPRSS2 could be used as biomarkers by evaluating the stability of primary tumor cells grown in 2D or 3D culture media." (PMID 30792990, 2019). "The abnormal expression of PAX5, a member of the PRD-type subclass, derived from chromosome translocation with the IGH locus can deregulate the lymphoid cell gene expression program and contribute to B and T-lineage neoplasms." (PMID 29572508, 2018). "Therefore, the tumour cells lack expression of most B-cell markers and transcription factors OCT2 and BOB1; however, the weak expression of PAX5 confirms the B cell origin of the tumour cells." (PMID 29518976, 2018). "Tumor cells showed CD30, CD15, and PAX-5 gene product positivity." (PMID 29051894, 2017). "Recently, a retrospective study conducted a double staining of PD-L1 and PAX5 in DLBCL samples in order to precisely quantify the rate of PD-L1+ cells in both the tumor and non-tumor compartments." (PMID 28402953, 2017). "Despite these observations, we were unable to correlate Pax-5 signature patterns to specific mammary pathologies, tumor grade or staging (data not shown)." (PMID 28076843, 2017). "Abundance of Ikzf1 and Pax5 transcription factor mRNA was not significantly different in tumor vs unaffected cells, but was markedly lower than in pre-B cells from wild-type and Bcl-xLTg mice." (PMID 28692033, 2017). "In this study we found that PAX5 was generally highly expressed in normal adult tissues while the expression of which was frequently down‐regulated or lost in NSCLC cell lines, and primary tumour tissues compared with their adjacent non‐tumour tissues." (PMID 26843424, 2016). "We next evaluated tissue from tumor bearing mice (tumor mass, spleen, intestine and kidney) by immunohistochemical analysis for the expression of CD3, CD5, CD19, CD20, CD23, CD45, CD79a, Ki-67, cyclin D1, and Pax5." (PMID 24722054, 2014).
tumor (continued). "Immunohistochemically, the tumor cells were strong positive for CD56, CD3ε, TIA1, and weak positive for LMP1, and negative for CD5, CD8, CD20, CD79a, CgA, Syn, SCLC, CK, EMA, CD99, CD10, TdT, PAX-5, and BCL-6." (PMID 23958352, 2013). "Further staining in other areas of the tumor revealed solid areas of CD20+CD79a+PAX-5+CD43+ positive cells that lacked T-cell antigens and EBER RNA." (PMID 23738160, 2013). "As expected, PAX5 staining revealed a general diffuse cytoplasmatic staining of B-cell areas, varying greatly between samples (especially in the DLBCL samples once again), which might mirror different percentages of tumor infiltration in the tissue." (PMID 41373408, 2025). "By immunohistochemistry, the tumor cells expressed synaptophysin, chromogranin, NKX2.2 (diffuse, nuclear), GFAP (patchy), SMI31 (neurofilament) (focal, cytoplasmic), and TdT (diffuse, nuclear), while lacking expression of CD99, TTF-1, CK 20, MCPyV, PHOX2B, Olig2, OCT3/4, CD45, CD3 and PAX5." (PMID 38031161, 2023). "However, many large-scale and functional genomic analyses commonly demonstrate that the tumor suppressive features of PAX5 are inhibited by promoter hypermethylation events in non-hematological cancers." (PMID 36077495, 2022). "In addition to cases containing PD-L1+ large bizarre-shaped tumor cells, there were also cases with PD-L1+ nonmalignant stromal cells, and we defined them as mPD-L1+ (PD-L1+/PAX5-)." (PMID 34221962, 2021). "This may be due to the origin and source of tissue samples tested (all consisting of primary tumor specimens) which do not represent Pax-5 expression profiles in circulating tumor cells or metastatic niches." (PMID 28076843, 2017). "The observation that PAX5 was frequently silenced by promoter hypermethylation in NSCLC but not in normal lung tissues led us to hypothesize that PAX5 is a candidate tumour suppressor in NSCLC." (PMID 26843424, 2016). "Immunohistochemistry confirmed DLBCL (germinal center B-cell subtype), with tumor cells positive for Oct-2, CD20, PAX5, BCL-6, and CD10 and negative for CD38, CD138, and MUM1." (PMID 40432631, 2025). "Consistent with EMP in other locations, all neoplasms in our cases were MUM-1-positive, variably positive for CD20 and CD79, and negative for PAX5 and CD3." (PMID 40215400, 2025). "Morphologically, the tumor comprised a subset of lymphoid cells with centrocytic morphology that was positive for CD20, PAX5, CD10, BCL6, and CD23, and negative for CD5 and BCL2." (PMID 40861583, 2025). "Immunohistochemical staining showed strong expression of CD20, CD79a, and PAX5 in tumor cells, but CD3, CD56, and TIA1 were not expressed in tumor cells." (PMID 41291370, 2025). "IHC confirmed the diagnosis of DLBCL (germinal center B-cell subtype), as the tumor cells were positive for Oct-2, CD20, PAX5, BCL-6, and CD10 and negative for CD38, CD138, MUM1, and CD30." (PMID 40432631, 2025). "The tumor cells expressed the B cell markers CD20, CD79a, and PAX-5 but were negative for CD3, ER, and PR." (PMID 37884941, 2023). "One case was diagnosed as ‘suggestive of HL’ histologically based on many eosinophils and histiocytes without the presence of typical RS cells and atypical tumor cells showed positivity for CD30 and PAX5 while CD3, CD20, and EBER-ISH were negative." (PMID 36614926, 2022). "In summary, these data demonstrate that Pax5‐Jak2 expression from the Pax5 locus initially did not interfere with normal B cell development in young mice, but then rapidly led to the development of an aggressive B‐ALL tumor." (PMID 35156727, 2022).
tumor (continued). "Immunohistochemical analysis of the left pleural biopsy specimens suggested DLBCL, where the tumor cells were positive for CD20, PAX5, and BCL-2 but negative for CD10, BCL-6, Mum-1, and LMP-1." (PMID 33564306, 2021). "The tumor cells are positive for CD45, CD30, CD15, MUMi, and Ki-67 (80%) and negative for CD20, PAX-5, CD79a, CD3, CD5, CD10, BCL6, BCL2, EMA, ALK-1, and CD138." (PMID 34900354, 2021). "For the diagnosis of BPDCN, the tumor should be negative for other myelomonocytic, NK, T, and B lineage markers (CD34, CD8, MPO, lysozyme, PAX5, CD20, CD79a, EBV, and T-cell receptor protein)." (PMID 31752482, 2020). "IHC was mainly positive for tumor markers like CD10, CD20, CD45, CD 79a, PAX5, MUM1, and BCL6, and negative for BCL2, ALK, CD30, and cyclin D1." (PMID 30764662, 2018). "Immunohistochemical staining revealed that the large-sized tumor cells were positive for CD20, PAX-5, MUM-1 and BCL-2, and were negative for CD3, CD5, CD43, CD10, CD23, CyclinD1, CD138, CD30, ALK, CD56, MPO, S-100, TTF-1, thyroglobulin and calcitonin." (PMID 28841887, 2017). "The tumor cells are variably positive for CD20 and CD45, and express terminal B-cell differentiation markers such as MUM1, whereas they are negative for CD79alpha, PAX5, CD138, CD30, ALK, CD3 and EBER." (PMID 40869163, 2025). "The CD27-positive, CD38-positive, and PAX5-negative tumor-induced plasmablast-like-enriched B cell (TIPB) population regulates T cell-recruiting chemokines (CCL3, CCL4, and CCL5) and increases the number of tumor-infiltrating T cells." (PMID 36361781, 2022). "A majority of ALK-negative ALCL tumor cells are positive for CD3 and negative for CD15 or PAX5." (PMID 33126356, 2020). "A routine immunohistochemistry antibody panel revealed that the tumor cells were negative for B-cell and T-cell markers (i.e., CD3, CD19, CD20, CD38, CD45RO, CD79a, CD138, and Pax-5), but were positive for CD30 and MUM-1, not defining the lineage of tumor cells." (PMID 28143608, 2017).
cancer (78 papers, 2011 to 2026). A tumor composed of atypical neoplastic, often pleomorphic cells that invade other tissues. "While studying the underlying mechanism of Pax5 expression in NE-like cancer, we observed the involvement of Pbx1 in Pax5 transcription." (PMID 38168280, 2023). "The cancer-immune cell interaction is associated with the activation of a PAX5 module that is enriched in regions with an increased presence of B cells." (PMID 37723590, 2023). "Given its crucial function in B-cell development, PAX5 aberrant expression also correlates with hallmark cancer processes leading to hematological and other types of cancer lesions." (PMID 36077495, 2022). "Despite the well-established association of PAX5 in the development, maintenance, and progression of cancer disease, the use of PAX5 as a cancer biomarker or therapeutic target has yet to be implemented." (PMID 36077495, 2022). "About one-third of cancers are consequences of PAX5 gene modifications, and the complete loss of this gene is related to the highest aggressiveness of B-cell ALL." (PMID 35330370, 2022). "In most cases, deregulated PAX5 expression impedes the progression of B-cell differentiation leading to hallmark cancer features such as proliferation, apoptosis, and phenotype transitioning processes." (PMID 36077495, 2022). "This identified 160 significant non-coding elements, including the TERT promoter, a well-known non-coding driver element, as well as elements associated with known cancer genes and regulatory genes (e.g., PAX5, TOX3, PCF11, MAPRE3)." (PMID 29354286, 2018). "The clusters of gene transcription, inflammatory and immune response, and cancer pathways were identified as three important pathways associated with PAX5 haploinsufficiency in Raji cells." (PMID 28316978, 2017). "In conclusion, our study here shows that changes in the gene transcription, inflammatory and immune response, and cancer pathways were identified as three important pathways associated with PAX5 haploinsufficiency." (PMID 28316978, 2017). "Recent reports have associated the transcription factors Pax2 and Pax5 with increased capabilities for cell motility and adhesion in human cancer." (PMID 22531031, 2012). "PAX5 haploinsufficiency caused the abnormal expression of genes involved in cancer pathways." (PMID 28316978, 2017). "miR-1343-3p suppresses autophagy by directly targeting ATG7, while miR-138 promotes cancer stem cell survival via repression of PAX5, offering rationale for miRNA-based reprogramming." (PMID 41596492, 2026). "Heatmap and functional annotation indicated that several significantly upregulated genes (CCL21, H2‐Eb2, Pax5, CD19, CD22, etc.)were associated with anti‐cancer immunity." (PMID 41306557, 2025). "Specifically, we target mutations within two key oncogenic molecules, PAX5 and MYC, aiming to elucidate their role in triggering cancer cell death using the CRISPR-Cas9 system." (PMID 39469218, 2024). "Although, ectopic expression of Pbx1 did not induce NE-like transition or morphology to the adenocarcinoma cells, however, its depletion from NE-like cancer affects neurite formation similar to Pax5 deletion." (PMID 39183332, 2024). "In this study, by comparing chromatin accessibility, epigenetic signatures, and gene expression between adeno and NE-like cancers, we have identified Pax5 as a transcription factor important during NE-like transformation." (PMID 38168280, 2023). "Our results indicate that Pax5 is involved in the transcription of specific neuronal gene signatures in NE-like cancers." (PMID 38168280, 2023). "Overall, our results suggest that Pax5 expression in NE-like cancer is pivotal to maintaining the cellular interaction by strengthening the neuronal adhesion interaction in NE-like cells." (PMID 38168280, 2023).